EGFR (epidermal growth factor receptor)
Diseases named in the same sentence as EGFR in open-access papers (continued):
Sharing a sentence is not in itself a finding about the gene and the disease.
adenocarcinoma (continued). "Additionally, the third most prevalent EGFR mutation is the exon 20 insertion mutation, known as EGFR ex20ins, which predominantly occurs in female, non-smoking individuals, and in adenocarcinoma tissue." (PMID 38919530, 2024). "Similarly, other studies have shown that the rates of positive EGFR mutations were higher among female patients with adenocarcinomas, particularly among nonsmokers." (PMID 37425232, 2023). "EGFR mutation is related to gender, ethnicity, smoking, and pathological type of patients, and the incidence of mutation is higher in the Oriental population, female, nonsmoking, and adenocarcinoma patients." (PMID 37390230, 2023). "The molecular classification of adenocarcinoma subgroup is established and is well known, where the most frequent genetic alteration among non-Asian patients is KRAS mutation (1/3) followed by EGFR (5%–15%) while in Asian patients EGFR mutation is the most frequent followed by KRAS mutation." (PMID 38239281, 2023). "In addition, adenocarcinoma (p < .001) and early pathological stages (p = .001) were more common; while lymphovascular invasion (p < .001), visceral pleural invasion (p = .001), and EGFR expression (p < .001) were less common." (PMID 36806719, 2023). "It was found that an increased expression of ERBB mRNA may play a role in NSCLC, particularly in females, non-smokers, adenocarcinoma patients, and those with an EGFR mutation." (PMID 36551663, 2022). "ASCL1 has been found to be associated with lack of EGFR mutations, PD-L1 negative expression, and a poor immune cell infiltration in adenocarcinomas with neuroendocrine differentiation, but not to characterize subsets of SCLC with a distinctive clinical outcome." (PMID 35608806, 2022). "In addition, EGFR mutations were demonstrated to be significantly associated with adenocarcinoma, never smoking, and the female gender." (PMID 35515138, 2022). "Furthermore, NSCLC adenocarcinomas expressing EGFR mutations are statistically more prevalent in female non-smokers." (PMID 35455447, 2022). "A previous epidemiological study has shown that several clinical factors (female, no smoking history, adenocarcinoma, and East Asian ethnicity) are associated with a high prevalence of EGFR mutations; however, there are no robustly predictive clinical features of EGFR mutation status." (PMID 36230590, 2022). "The demographics of patients with EGFR ex20ins mutations are similar to those of patients with classical EGFR mutations; ex20ins mutations are more common in women, nonsmokers, patients with adenocarcinoma and Asians." (PMID 35418149, 2022). "Interestingly, MMP-9 and pro-MMP-9 are notably elevated in serum-derived exosomes from patients with EGFR-mutated adenocarcinoma, and this is independent of stage, gender, age, or smoking history." (PMID 35954442, 2022). "In addition, wildtype EGFR was more commonly seen in male, smoker and non-adenocarcinoma." (PMID 34868942, 2021). "As a driver gene, EGFR may promote adenocarcinoma progression." (PMID 33442956, 2021). "EGFR mutation was more frequent in adenocarcinomas with MLCs than those without MLCs (P = 0.040)." (PMID 34234879, 2021). "Activated EGFR was reported to induce keratin 5 and keratin 14 expression and was associated with the keratin expression percentages in the immune class, while the non-immune class was mostly composed of adenocarcinomas." (PMID 33971902, 2021). "In the 16 EGFR-mutated patients, 15 had adenocarcinomas and 1 had a not-otherwise-specified NSCLC." (PMID 34696229, 2021). "In addition, adenocarcinoma samples, with and without epidermal growth factor receptor (EGFR) mutation, were also compared." (PMID 33374433, 2020).
adenocarcinoma (continued). "Histopathological and molecular analyses of transbronchial biopsy specimens from the right middle lobe revealed adenocarcinoma; the malignant epithelial cells were positive for carcinoembryonic antigen (CEA) and negative for synaptophysin, and they harbored an exon 19 deletion mutation in EGFR." (PMID 32762742, 2020). "Additional limitations included lack of a central review, the fact that less than 20% of the patients had adenocarcinomas, no assessment of the expression of EGFR and mutations in the vast majority of the patients, and lack of standardized procedures of treatment planning and quality assurance." (PMID 32533228, 2020). "The roles of TLG and MTV as significant predictive markers after anti-PD-1 antibody therapy may be closely associated with patients with a histology of adenocarcinoma and without EGFR mutation." (PMID 32156047, 2020). "No EGFR or ALK mutation were detected in patients with adenocarcinoma." (PMID 32833338, 2020). "However, typical biomarkers for adenocarcinoma, such as EGFR mutations and ALK abnormalities, were not adequately examined because of the old times of some enrolled patients." (PMID 33183251, 2020). "However, four patients with EGFR mutation adenocarcinoma did not receive the targeted therapy, including one patient who refused, while the other three had died before the molecular report was available." (PMID 32767461, 2020). "Among the stage IV adenocarcinoma patients tested for EGFRms (n=129), EGFR-TKIs were prescribed as a first-line treatment in 14 cases; 27 (out of 31) patients with stage IV adenocarcinoma and positive EGFR mutations received an EGFR-TKI treatment (data not shown)." (PMID 33084767, 2020). "GGO volume percentage in adenocarcinomas with EGFR mutation was significantly higher than that in tumors without EGFR mutation, and adenocarcinomas with exon 21 mutation showed significantly higher GGO volume percentage than in tumors with exon 19 mutation and those without EGFR mutation." (PMID 30956990, 2019). "According to the association analysis for EGFR mutation in patients with adenocarcinoma (n = 108, EGFR mutant = 64), we found 159 suggestive DMPs and six significant DMPs (cg09245319, cg17183999 [USP7], cg06366994 [CPE], cg24992236 [MEG9], cg22144719, and cg22448179 [EGFR])." (PMID 31450665, 2019). "Interestingly, miR-130b expression was high in NSCLC tissues, regardless of histologic subtypes and of the presence or absence of epidermal growth factor receptor gene mutation in adenocarcinoma specimens." (PMID 31061410, 2019). "In this study, we examined whether GGO volume percentage determination through routine CT may noninvasively differentiate adenocarcinomas with EGFR mutations from those without EGFR tumors, with the benefit of not incurring adding additional costs." (PMID 30956990, 2019). "EGFR mutations occur mainly in adenocarcinoma, younger women, and never-smokers." (PMID 30777071, 2019). "In addition, all studies concluded the presence of a correlation between EGFR mutation status and female sex, non-smoking status, and adenocarcinoma subtype." (PMID 30217176, 2018). "A 72-year-old Japanese male presented with an abnormal chest opacity that was determined to be adenocarcinoma of the left upper lobe at cT2aN1M1b Stage IV, without epidermal growth factor receptor (EGFR) mutation and anaplastic lymphoma kinase (ALK) translocation." (PMID 29554874, 2018). "Similarly, female, never-smokers, brain metastasis and adenocarcinoma were associated with a higher rate of EGFR mutations in this study." (PMID 30337598, 2018). "In addition, adenocarcinoma with micropapillary morphology has a higher frequency of EGFR mutations than adenocarcinoma without this morphology." (PMID 29538329, 2018). "This may be due to the inclusion of patients with pure adenocarcinoma, a greater number of non-smokers, a higher EGFR mutation rate among the Taiwanese patients, and the integration of EGFR-TKI treatment." (PMID 29228697, 2017).
adenocarcinoma (continued). "The total mutation rate of EGFR gene was 36.70%, major occurred in exon 19 (36.61%) and exon 21 (51.36%), respectively, and EGFR mutations usually occurred in female, non-smoking and adenocarcinoma patients (P < 0.05)." (PMID 28103968, 2017). "Moreover, unlike adenocarcinomas, lung SCCs rarely harbor EGFR and ALK mutations, thus, until very recently, there has not been significant improvement in their treatment." (PMID 28653990, 2017). "Notably, 4 of the glucose metabolism-related genes, GPI, G6PD, PKM2, and GAPDH and 5 of the cell cycle-related genes, ANLN, PTTG1, CIT, KPNA2, and CDC25A, were significantly down-regulated in EGFR m+ adenocarcinomas, and showed a substantial correlation with SUVmax." (PMID 28422979, 2017). "In addition, the patient had negative test results for epidermal growth factor receptor (EGFR), K-ras, and anaplastic lymphoma kinase mutations, all consistent with adenocarcinoma." (PMID 28859661, 2017). "In addition, mutant epidermal growth factor receptor (EGFR) makes up 10%–40% in adenocarcinoma." (PMID 28208579, 2017). "EGFR mutation statuses were positive in 8 adenocarcinomas, while the other 8 were negative." (PMID 28877268, 2017). "Similarly, a 2011 retrospective online survey of patient records found that China had the lowest rate of EGFR gene mutation testing of the 6 Asian Pacific countries assessed, with 18.3% of all NSCLC patients and 30.3% of NSCLC patients with adenocarcinoma histology tested." (PMID 28673332, 2017). "Female, non-smoker and adenocarcinoma histology were predictor of having positive EGFR mutation." (PMID 27930702, 2016). "The repeat biopsy also revealed an adenocarcinoma without EGFR mutation." (PMID 28293661, 2016). "Importantly, this was not the case for the MPE of the KRAS mutated but EGFR wild-type adenocarcinoma." (PMID 27548442, 2016). "For example, tumors that were classified as non-adenocarcinoma may have had an adenocarcinoma component, which may partially explain the higher than expected frequency of EGFR mutations among the non-adenocarcinoma categories." (PMID 27294665, 2016). "Also, a cross-talk of EGFR-MET was reported in adenocarcinomas with brain metastasis." (PMID 27018053, 2016). "However, EGFR mutations are most common in Asian patients, nonsmokers, females and those with adenocarcinoma histology." (PMID 27623437, 2016). "Since all patients with stage 3b and 4 NSCLC were not tested for EGFR mutations in that study, the 39% EGFR prevalence reported in adenocarcinoma patients could be considered to be an overestimate." (PMID 27483001, 2016). "The aim of this study is to analyze whether or not clinical-selected patients (Asian, adenocarcinoma histology, non-smoking) and EGFR mutation-selected patients benefit from EGFR-TKIs or chemotherapy." (PMID 25800570, 2015). "In addition, these findings confirm the expected ability of mutant RAS to render EGFR-mutant adenocarcinoma cells resistant to TKI's and further enhance the significance of not observing oncogenic KRAS mutations in human tumors resistant to erlotinib (see ‘Discussion’)." (PMID 26047463, 2015). "In conclusion, the results of the present study indicated that intercalated treatment with chemotherapy and EGFR TKIs does not improve ORR, PFS, and OS compared to chemotherapy alone in patients in a clinically selected population excluding patients with non-smoking adenocarcinoma or mutated EGFR." (PMID 26493267, 2015).
adenocarcinoma (continued). "In addition, their results indicated that EGFR gene mutation could be the predictive factor for the response to TKIs, although the efficacy was lower for SQCLC than for adenocarcinoma." (PMID 25886585, 2015). "EGFR mutations were more common in females, never smokers, and patients with adenocarcinomas." (PMID 26555338, 2015). "Non-smoking patients with adenocarcinoma or patients with activating EGFR mutation were excluded because they could benefit from gefitinib alone." (PMID 26493267, 2015). "However, HNSCC and adenocarcinomas of the colorectal region are EGFR positive or highly positive." (PMID 26452257, 2015). "Results of the IPASS phase 3 trial, conducted in a population of 1217 patients with clinical characteristics predictive of EGFR mutations (namely East Asian nonsmokers with adenocarcinoma), provide additional support for the activity of gefitinib in this setting 24,25." (PMID 26310719, 2015). "Besides a different ethnicity distribution, EGFR mutations are also suggested to be more common in adenocarcinoma, women, and never-smokers." (PMID 26599344, 2015). "An overwhelming majority of TTF-1 negative adenocarcinomas will be negative for EGFR mutations." (PMID 25594059, 2014). "Indeed, 21.1% of our Japanese study population was non-smokers, 42.1% of whom had adenocarcinoma with EGFR mutation." (PMID 24498965, 2014). "All the patients had adenocarcinoma that was negative for EGFR mutations." (PMID 25501361, 2014). "This suggests that KRAS mutated AAH may not progress to adenocarcinoma in the same way proposed for EGFR mutated AAH, and that KRAS mutations occur in adenocarcinoma de novo via an alternative pathogenesis." (PMID 24742923, 2014). "On the other hand, many studies suggest that the increasing incidence of adenocarcinoma in Asian populations including the Japanese population might be associated with epidermal growth factor receptor (EGFR) mutation rather than with smoking." (PMID 24498965, 2014). "However unlike Caucasians, EGFR mutation rate among adenocarcinoma-never-smoker females were comparable to males suggesting lack of gender bias among never smokers likely to benefit from EGFR targeted therapy." (PMID 24124538, 2013). "Due to the fact that the patient possessed clinical features including a history of never smoking, adenocarcinoma histology, female gender and Asian ethnicity, gefitinib was chosen as the second-line treatment, even though the patient did not exhibit EGFR gene mutations." (PMID 23761825, 2013). "The frequency of EGFR mutation status detected by Scorpion ARMS was statistically significantly more frequent in women (140/233 or 63.3%) than in men (81/253 or 36.7%), and more frequent in adenocarcinomas (220/467 or 47.1%) than in other histology (1/17 or 5.9%)." (PMID 23590575, 2013). "Numerous reports have confirmed that the efficacy of EGFR-TKIs correlates with EGFR exon mutations, and that the incidence of EGFR mutations is higher among Asians, non-smokers, females, and patients with adenocarcinoma." (PMID 23341890, 2013). "Supporting evidence for this hypothesis includes the disproportionately higher proportion of adenocarcinoma and EGFR mutations in lung tumors among never-smokers, along with additional clinical and pathological differences between the two tumors." (PMID 23940620, 2013). "EGFR-mutated adenocarcinomas were more common in female never smokers than KRAS mutations." (PMID 24179496, 2013). "Further analysis indicated in the 32 cases of non-smoking, female, adenocarcinoma patients that the frequency of EGFR exon mutations and EML4-ALK translocation were 62.5%% (20/32) and 15.63% (5/32), respectively, which covers all 78.13% (25/32) of these patients." (PMID 23341890, 2013). "In light or never-smoking Asian patients with adenocarcinoma, the rate of EGFR mutations may be as high as 60%." (PMID 22263108, 2012). "However, EGFR may be overexpressed in esophageal cancer, either in adenocarcinoma or squamous cell carcinoma." (PMID 22792097, 2012).
adenocarcinoma (continued). "Among never smokers with adenocarcinoma, the proportion of EGFR mutations increases to ∼50%." (PMID 22374459, 2012). "Notably, the frequency of ALK fusions in patients with adenocarcinomas that did not exhibit EGFR/KRAS mutations reached 45.0% (9/21), strongly indicating that only a specific molecular subset of adenocarcinomas is characterized by EML4-ALK fusion." (PMID 20624322, 2010). "The survival benefit was particularly large in patients with adenocarcinoma histology and was not driven by the EGFR-mutation positive subgroup, with a significant improvement in survival observed in the EGFR wild-type group ultimately leading to FDA-approval of erlotinib in this indication." (PMID 21165163, 2010). "These mutations consisted of 19 KRAS (24.7%), 10 EGFR (13%), five BRAF (6.5%), four PIK3CA (5.2%), one HER2 (1.3%), one HER4 (2.2%) and none for HER3. mEGFR, mBRAF and mHER2 were present exclusively in adenocarcinomas while mKRAS were more frequent in adenocarcinoma and large cell histologies." (PMID 19238210, 2009). "EGFR mutation rate was high in females, never-smokers and patients with adenocarcinoma." (PMID 17387341, 2007). "Moreover, multivariate analysis has shown that adenocarcinoma histology and never-smoker status are independent factors associated with EGFR mutation." (PMID 17387341, 2007). "The adenocarcinoma samples that had EGFR mutations did not present with KRAS mutations." (PMID 17184525, 2006). "Although EGFR mutations itself is not a predictor for a better survival in adenocarcinoma patients as shown in both the present study and a previous study, EGFR mutations were good predictor of the clinical benefit with patients with gefitinib treatment in such patients." (PMID 16552419, 2006). "As 36 of the 39 patients (92.3%) enrolled in this study had adenocarcinoma, we could not evaluate differences in the frequency of the EGFR mutations according to the histological type." (PMID 17060940, 2006). "There were significant differences between EGFR mutation-positive and EGFR mutation-negative groups with regard to sex (male vs female: P=0.00001), histology (adenocarcinoma vs non-adenocarcinoma: P=0.02) and smoking (>20 pack-years vs <20 pack-years: P=0.003)." (PMID 17106442, 2006). "Adenocarcinomas with EGFR mutations displayed inclusion of bronchio-alveolar component, or well-to-moderately differentiated features, which are also one of the histological features of adenocarcinomas in nonsmokers." (PMID 16052218, 2005). "Moreover, reports objecting peoples in East Asia reported a half of adenocarcinomas in East Asia patients had EGFR mutations and the absence of smoking history, mainly seen in female patients, were closely linked to EGFR mutations." (PMID 16052218, 2005). "In addition to higher incidence of EGFR mutations in adenocarcinomas developed in nonsmokers, we showed that the incidence of EGFR mutations was higher in former smokers than in current smokers." (PMID 16052218, 2005). "Unlike K-ras mutations involved in adenocarcinomas developed in smokers, however, EGFR gene mutations may play a key role in the development of adenocarcinomas in nonsmokers." (PMID 16052218, 2005). "Comparative profiling revealed higher EGFR and EPCAM expression in HNSCC versus NSCLC, while MUC1 predominated in NSCLC, particularly in SQCCL; notably, the NSCLC cohort was predominantly adenocarcinoma." (PMID 42203995, 2026). "Immunohistochemistry for DARPP-32 isoforms DARPPN and DARPPC, EGFR, D2R, and VEGFR2 was used to assess 46 canine adenocarcinomas." (PMID 40969344, 2025). "An updated analysis for patients treated from 2006 to 2014, which included EGFR and ALK status, showed improved survival up to 12 months overall with 15.2 months for adenocarcinoma and 9.2 months for non-adenocarcinoma patients." (PMID 40427102, 2025).